U2 (U2 spliceosomal RNA )
Synonyms: LOC124904137
Gene: Small nuclear RNA gene on chromosome 17 (43,245,674 to 43,245,864, reverse strand). Ensembl gene ENSG00000274432.
Gene Ontology:
Molecular function: pre-mRNA branch point binding
Biological process: mRNA branch site recognition
Cellular component: U2 snRNP
Homologues: Orthologues: chimpanzee U2 (100% identical), macaque U2 (100% identical), dog U2 (99% identical), pig U2 (48% identical), rat LOC120094029 (36% identical). Paralogues in human: U2 (100% identical), RNU2-2 (96% identical), U2 (95% identical), RNU2-3P (93% identical), RNU2-4P (93% identical), RNU2-17P (90% identical), RNU2-6P (90% identical), RNU2-48P (89% identical), RNU2-52P (89% identical), RNU2-59P (89% identical), RNU2-25P (87% identical), RNU2-26P (87% identical), and 68 more.